GATA3 (GATA binding protein 3)
Diseases named in the same sentence as GATA3 in open-access papers (continued):
Sharing a sentence is not in itself a finding about the gene and the disease.
asthma (continued). "A novel therapy for the treatment of Th2‐driven asthma targeted GATA3, a transcription factor that plays a key role in Th2 cell differentiation, through an inhaled DNA enzyme (DNAzyme) that specifically cleaves and inactivates GATA3 mRNA." (PMID 33133517, 2020). "CD4+ T cells from the asthma group showed higher expression of the Th2 master transcription factor Gata-3 and decreased expression of the Th1 master transcription factor T-bet." (PMID 31231429, 2019). "ESI-09 treatment increased, whereas 8pCPT treatment decreased the expression of GATA3 in asthma mice." (PMID 31852500, 2019). "Signal transducer and activator of transcription (STAT) 6 has been identified as a mediator of asthma, inducing the expression of the Th2 master regulator GATA-3, which is responsible for the expression of Th2 cytokines." (PMID 30823378, 2019). "We identified three novel genome-wide significant genetic associations that imply MUC5AC, GATA3, and KIAA1109 have an association with susceptibility to the development of moderate-to-severe asthma." (PMID 30552067, 2019). "The increased expression of GATA3 (thus defined as th2 cell) was reduced in the asthma group following CLE treatment group." (PMID 30783201, 2019). "Th1 cytokines, such as IFN-γ, inhibit allergen-induced eosinophil recruitment and IgE release via downregulating GATA-3, IL-4, and IL-5 expression in the lung tissues of asthma model." (PMID 29991953, 2018). "Similar immunotherapeutic programs such as GATA3 can introduce novel therapeutic agents to modulate inflammation in patients with asthma." (PMID 30116273, 2018). "And we also found that FEV1%pred of patients with asthma was correlated with the percentage of GATA3+ Treg cells." (PMID 30013989, 2018). "The increased serum IL-4 levels and elevated expression of GATA3 in patients with asthma confirmed a deviation toward Th2 cells in patients with asthma that play a prominent role in pathogenesis of allergic asthma." (PMID 30116273, 2018). "The results of the current study indicated that the serum level of IL-4 and GATA3 expression were significantly higher in patients with asthma compared with the healthy individuals." (PMID 30116273, 2018). "GATA3/FOXP3 ratio in PBMCs isolated from patients with asthma was significantly higher than that of healthy subjects (9.49±2.02 vs. 3.48±0.78, P<0.004)." (PMID 30116273, 2018). "The results of the current study also indicated that GATA3/FOXP3 expression ratio in patients with asthma was significantly higher than those of healthy individuals." (PMID 30116273, 2018). "The GATA3 expression in PBMCs isolated from patients with asthma was significantly higher than that of the healthy subjects (3.30±0.51 vs. 1.15±0.10, P<0.001)." (PMID 30116273, 2018). "We found that the frequencies of GATA3+IL-4+, GATA3+IL-5+, and GATA3+IL-13+ CD4+ T-cells in the lungs of asthma-induced Bcl11bfl/fl dLck-iCre mice were reduced, as were the frequencies of GATA3+, IL-4+, IL5+, and IL-13+ CD4+ T-cells." (PMID 29700302, 2018). "The levels of GATA-3 was significantly different between the asthma group and the control group in both tissues in mice treated witheitherST or TT." (PMID 28769099, 2017). "Different transcription factors, such as STAT-6, GATA-3, activator protein 1 (AP-1), and NF-κB, are involved in the pathogenesis of asthma." (PMID 28974953, 2017). "STAT-6 and GATA-3 are reported to be central players in PARP-1-mediated eosinophilic inflammation in asthma." (PMID 28974953, 2017). "The mechanisms of asthma and eczema were found to be identical for three pathways: Regulation of hematopoiesis by cytokines, GATA3 participate in activating the Th2 cytokine genes expression, and CCR3 signaling in eosinophils." (PMID 28598986, 2017). "As a new DNAzyme targeting GATA3 mRNA in TH2 cells entered Stage III clinical trials in treating asthma, These findings provide potential future therapeutic targets for peripheral T cell lymphoma." (PMID 27589565, 2016).
asthma (continued). "GATA binding protein 3 (GATA-3) is identified as an important transcription factor of mast cells and Th2 cells, which are key effector cells in the pathogenesis of AR and asthma through releasing inflammatory mediators and cytokines upon exposure to allergens." (PMID 27187364, 2016). "To further understand the mechanism whereby Th2 response is enhanced in B7-H3 KO mice, we analyzed the expression of GATA3, a principal transcriptional activator of Th2 cell differentiation, in the splenocytes of wt and B7-H3 KO mice with induced asthma." (PMID 26065426, 2015). "The expression levels of GATA3 and miR-125a-5p were significantly upregulated in the Treg cells of asthma patients compared with healthy donors." (PMID 26424054, 2015). "Focussing on genes of the Th2 pathway (IL4, IL4R, IL13, GATA3, STAT6), the authors demonstrated that the odds of asthma tended to decrease at the age of 10 years with increasing GATA3 methylation." (PMID 26052354, 2015). "In the present study, the ratio of T-bet to GATA-3 decreased in the asthma group compared with that in the control group and was partly reverted in the afzelin treatment groups." (PMID 25738969, 2015). "Our findings showed that the levels of Notch1 and Notch2 receptors were up-regulated in asthma group, accompanied by the increased expression of GATA3." (PMID 24706026, 2014). "Asthma being considered mainly a ‘Th2 disease’, we focused on the GATA3 gene because it is known to be the master regulator of Th2 cell differentiation and has been linked to endocrine responses." (PMID 25250096, 2014). "Both in vivo and in vitro studies confirmed that Vitamin A and ATRA induce Th2 bias and promote Th2 cytokines realise, such as IL-4, IL-5, IL-13 and GATA-3, which is one of the major characteristics of asthma." (PMID 24204796, 2013). "In mild asthma, the largest change (9-fold) was observed in Foxp3 expression followed by Tbet, Gata3, and Rorγt." (PMID 23781124, 2013). "In an experimental mouse model of allergic induced-asthma, 1,25(OH)D up-regulated the message expression of GATA-3." (PMID 22405472, 2012). "Major transcription factors controlling Th1 and Th2 development, such as T-box transcription factor and GATA3, are possibly involved in asthma and atopic diseases." (PMID 19534795, 2009). "We also studied the effects of inhaled fluticasone therapy on GATA-3 subcellular localization in peripheral blood mononuclear cells (PBMCs) from patients with asthma." (PMID 19436703, 2009). "We also demonstrated that inhaled fluticasone inhibits GATA-3 nuclear translocation in peripheral blood lymphocytes of patients with asthma in vivo." (PMID 19436703, 2009). "Inhaled FP (500 μg) treatment of seven steroid-naive asthma patients significantly reduced GATA-3–importin-α interaction in vivo in a time-dependent manner." (PMID 19436703, 2009). "PPAR-α and PPAR-γ ligands also decrease antigen-induced airway hyperresponsiveness, lung inflammation and eosinophilia, cytokine production, and GATA-3 expression as well as serum levels of antigen-specific IgE in many different animal models of asthma." (PMID 18315837, 2008). "The GATA-3 study design serves as an example of the first placebo-controlled trial to evaluate the glucagon-like peptide 1 receptor pathway’s role in asthma management independent of weight loss." (PMID 41567689, 2026). "Notably, quercetin has also been shown to regulate the Th1/Th2 balance by upregulating Th1 cytokine levels and suppressing Th2 cytokine levels through modulation of T-bet and GATA-3 gene expression in an experimental asthma model." (PMID 40843004, 2025). "Although the pathways that mediate PGAP3 induced ASM proliferation and contractility are not known, RNA-Sequencing of ASM expressing PGAP3 identified four genes significantly upregulated by PGAP3 that have known relevance with asthma (i.e., GATA3, ALOX5, BMP4, and SERPINB5)." (PMID 40131902, 2025).
asthma (continued). "Analyzing additional SNPs in STAT6 (e.g., rs324015, rs3024944, rs71802646) and other genes (e.g., IL1RL1, GATA3, ADAM33, TSLP, FOXO3a) would expand the scope of genetic analysis and provide a comprehensive understanding of asthma susceptibility in the population." (PMID 40375219, 2025). "GATA3 is a transcription factor which regulates T2 responses in asthma." (PMID 40131902, 2025). "DNA‐PKcs regulates the CD4+ T cells differentiation into Th1 and Th2 cells by Gata3 and Tbet in asthma, whether the similar mechanisms exist in other diseases remains to be explored." (PMID 38898995, 2024). "For example, FABIO highlighted GATA3 as important for asthma and ABCG2 for gout." (PMID 39621803, 2024). "The T-bet/GATA3 ratio was also reduced markedly in asthma groups (P<0.001)." (PMID 36311189, 2022). "Higher RORγt and GATA3 detection noted with E2 (severe asthgma+E2) as compared to severe asthma." (PMID 36062195, 2022). "The transcription factor GATA-3 controls the expression and production of IL-3, IL-5, and IL-13, which is essential for type 2 inflammation and is overexpressed in patients with CRSwNP, asthma, and atopic eczema." (PMID 36291990, 2022). "The central role of GATA-3 in the underlying immune pathways for the development of inflammatory allergic responses, and its significantly increased expression in the airways of asthma patients, support GATA-3 as a novel target for therapeutic intervention in type-2-driven asthma." (PMID 33917396, 2021). "Similarly, real-time PCR confirmed a substantial increase in the expression of key transcription factors GATA3 and RORγt in the adoption/asthma group." (PMID 34394777, 2021). "In addition to known variants already detected in study addressing general asthma previously, three novel loci harboring MUC5AC, GATA3, and KIAA1109 with convincing biological plausibility emerged." (PMID 32060620, 2020). "GATA3 inhibitor ameliorates Th2 allergy symptoms including asthma and AD." (PMID 32235696, 2020). "The results reveal that dexamethasone and Majie Cataplasm could prohibit the overexpression of STAT6 mRNA and GATA-3 mRNA in the asthma model group, while the effect of the two drugs rarely align for T-bet mRNA." (PMID 32489402, 2020). "GATA-3 induces Th2 cell development by promoting Th2 cytokine expression, but simultaneously inhibits Th1 differentiation by inhibiting T-bet, and thus plays a critical role in asthma." (PMID 30541898, 2019). "Identification of the GATA3 and KIAA1109 signals further extend the data that genetic variants in these regions are associated with asthma, potentially via eosinophilia and allergic sensitisation, two drivers of asthma that are also important in moderate-to-severe disease." (PMID 30552067, 2019). "Several direct links between those major compounds and the inhibition of the GATA-3/Th2 responses have been reported; for example, Camellia japonica oil suppressed asthma occurrence through the GATA-3, IL-4, and IL-5 pathways and its effective and major component is oleic acid." (PMID 30823378, 2019). "The strength of our study is that we were able to confirm that - based on a biomarker signal of elevated sputum eosinophils - a reduction in airway eosinophilia can be achieved by the GATA3-specific DNAzyme similar to the reduction observed in in asthma patients before." (PMID 29615049, 2018). "Among these transcription factors, GATA3 is crucial for the function of Treg cells in limiting Th2-type inflammatory responses, which indicates that GATA3 in Treg cells may be relevant to the pathogen of asthma." (PMID 30013989, 2018). "Therefore, Huai Qi Huang increased the ratio of not only T-bet/Gata-3 but also Foxp3/RORγt, regulating the balance of Th1/Th2 and Treg/Th17 in asthma." (PMID 29162668, 2017).
asthma (continued). "Notably, treatment with a DNA enzyme that cleaved GATA3 mRNA resulted in reduced airway eosinophilia and plasma levels of IL-5 in individuals with asthma, highlighting the feasibility of targeting TFs in patients with eosinophil disorders." (PMID 28791289, 2017). "In the context of asthma, GATA-3 has been found to be modulated by miR-126 in an indirect way." (PMID 27187364, 2016). "Our published work has already shown how GATA3 expression is high in Treg cells of asthma patients." (PMID 26424054, 2015). "Salidroside, a synthetic compound originally from Chinese herbal medicines, improved the progression of asthma, and could be used as a therapy for patients with allergic asthma by regulating the GATA-3/T-bet balance." (PMID 26075017, 2015). "A two-stage model consisting of genetic variants in the GATA3 gene, OCP use, age at menarche, and DNA-M may explain how sex hormones in women can increase the asthma prevalence after puberty." (PMID 25250096, 2014). "Tbet showed the largest change in expression in severe asthma followed by Foxp3, Gata3, and Rorγt." (PMID 23781124, 2013). "Finally, when the researchers treated seven patients with mild asthma with inhaled fluticasone, they found that fluticasone also inhibited GATA-3 nuclear translocation in the lymphocytes circulating in the patients' blood." (PMID 19436703, 2009). "However, it is likely that the higher concentrations of FP in the airways after inhaled administration would be effective in inhibiting GATA-3 in airway T cells of asthma patients." (PMID 19436703, 2009). "Many transcription factors (for example NF-κB, AP-1, GATA-3, STAT-1 STAT-6, c-Maf, NFATs and SOCS) have been implicated in the differentiation of Th2 lymphocytes and therefore represent therapeutic targets for asthma." (PMID 18315837, 2008). "Furthermore, overexpression of GATA-3 leads to increased airway remodelling in a mouse model of chronic experimental asthma." (PMID 18315835, 2008). "So due to its central role within the pathology of asthma GATA-3 represents an interesting target for new anti-allergic strategies, that might even be able to interfere with processes that ultimately lead to airway remodelling." (PMID 18315835, 2008). "Regarding the role of GATA3 in Th2-differentiation, Tiwari and colleagues reported that nuclear receptor subfamily 1 group D member 1 (Nr1d1) suppressed Th2 cell differentiation and attenuated asthma by acting as a transcriptional repressor of the GATA3 promoter [37••]." (PMID 36520269, 2023). "Interestingly, either the overexpression of Nr1d1 or the treatment with its ligand (SR9011) protected mice against lung inflammation in an asthma model (as shown by lung histology, reduced histological scores, IL-4-, IL-5-, and IL-13-levels, as well as reduced GATA3 expression) [37••]." (PMID 36520269, 2023). "Another therapeutic goal in asthma patients could be to modify the T-bet/GATA-3 ratio." (PMID 36311189, 2022). "Some scholars found that in an OVA-induced mouse asthma model, Que could regulate the expression of the T-bet and GATA-3 genes and affect the production of Th1/Th2 cytokines, resulting in a decrease in the IL-4 level of Th2 cytokines and an increase in the IFN-γ level of Th1 cytokines." (PMID 34838003, 2021). "However, GATA3 expression was significantly higher in asthma mice than that in control mice." (PMID 31852500, 2019). "Therefore, the T-bet/GATA-3 ratio may be used to evaluate the immune balance of Th1/Th2 responses in asthma." (PMID 25738969, 2015). "The remaining three IL-22 activators were all candidate genes for asthma alone: GNA15, SESN1, and GATA3, of which only GATA3 has been previously reported to directly activate IL-22 in ILC3s113." (PMID 41573945, 2026). "Type 2 T helper (TH2) GATA binding protein 3 (GATA3) is responsible for defining specialized TH2 cells, known for their proficiency in combating helminths and their involvement in allergies and asthma." (PMID 38835055, 2024).
asthma (continued). "Increased GATA-3 inhibits Th1 cytokine production through the inhibition of STAT4, resulting in a further increase in respiratory Th2 cells in asthma patients." (PMID 39060923, 2024). "Allergic diseases such as asthma, rhinitis, and eczema share several common pathways and proteins in the pathogenesis, such as the IL4 signaling and GATA3-related pathways." (PMID 38918763, 2024). "Asthma-related transcription factors that are activated by PKCθ include STAT6, NFAT, GATA3, and nuclear factor kappa B (NF-κB)." (PMID 37569348, 2023). "HES treatment in an ovalbumin (OVA)-induced asthma mouse model reduced IL-4, IL-5, IL-13, and IL-17 production, as well as OVA-specific IgE expression by inhibition of the GATA binding protein 3 (GATA3) transcription factor to the DNA." (PMID 35631330, 2022). "NOTCH1 is involved in the promotion of the GATA3-mediated Th2 response (immunity), which makes NOTCH1 an unlikely candidate responsible for the non-Th2 inflammatory pattern in asthma." (PMID 33980319, 2021). "Previous studies showed that both USP21 and PIM2 are regulators of GATA3 and FOXP3 expression, respectively, in Treg cells, so we measured the expressions of USP21 and PIM2 in Treg cells from patients with asthma and healthy subjects." (PMID 30013989, 2018). "We next evaluated the protein levels of GATA3 and Th2 cytokines in the T-helper cells of mice induced with HDM-asthma or infected with helminths." (PMID 29700302, 2018). "Overexpression of USP21 can rescue GATA3 from its degradation so as to stabilize the expression of GATA3; RT-PCR showed that the mRNA of USP21 is upregulated in the Treg cells of asthma patients." (PMID 30013989, 2018). "The serum levels of IL-4, the expression level of GATA3, and GATA3/FOXP3 ratio in patients with asthma were significantly higher than healthy subjects (P <0.002, P <0.001, and P <0.004, respectively)." (PMID 30116273, 2018). "There were 15 pathways involved in the multimorbidity of asthma, eczema and rhinitis, including IL4 signaling and GATA3-related pathways." (PMID 28598986, 2017). "These IL-6Rαhi CD8+ EM T cells produce high levels of Th2 cytokines and GATA binding protein 3 (GATA3), and are expanded in the peripheral blood mononuclear cells of asthma patients." (PMID 28732506, 2017). "Our data showed that GATA3, miR-125a-5p, FOXP3 and IL-6R are perturbed in the Treg cells of asthma patients." (PMID 26424054, 2015). "We hypothesized that interactions between genetic variants and methylation in genes in this pathway (IL4, IL4R, IL13, GATA3, and STAT6) influence asthma risk, that such influences are age-dependent, and that methylation of some CpG sites changes over time in accordance with asthma transition." (PMID 24735657, 2014). "And we found that in asthma groups, the expressions of NICD1 and GATA3 proteins were significantly increased than normal groups." (PMID 24706026, 2014). "Our data suggest that the therapeutic mechanism by which HPN effectively treats asthma is based on reductions of Th2 cytokines (IL-5), eotaxin, OVA-specific IgE production, and eosinophil infiltration via inhibition of GATA-3 transcription factor." (PMID 21772663, 2011). "Our results showed that, during acute asthma exacerbation, hsa‐miR‐155‐5p in AEC‐Exos regulates the differentiation of CD4+ T cells into Th2 type inflammation through the SIRT1 pathway, which was mediated through enhanced expression of STAT6 and GATA3." (PMID 38938285, 2024). "Overall, our results found that BGE inhibits allergic airway inflammation by negatively regulating the activation of PKCθ and asthma-related transcription factors (NFAT, NF-κB, GATA3, and STAT6) in mice with allergic airway inflammation as well as in EL4 cells." (PMID 37569348, 2023). "Silencing of MBD2 decreased the detection of RORγt in severe asthma significantly but not GATA3 which was counter confirmed by SiR-NC-MBD2." (PMID 36062195, 2022).